CRP (C-reactive protein)
Diseases named in the same sentence as CRP in open-access papers (continued):
Sharing a sentence is not in itself a finding about the gene and the disease.
lymphopenia (continued). "Repeat investigations revealed positive COVID-19 test, persistent absolute lymphopenia, and further elevation of D-dimer, LDH, ferritin, and CRP." (PMID 32918409, 2020). "The most prevalent laboratory results included elevated C-reactive protein (CRP), elevated lactate dehydrogenase (LDH), lymphopenia and decreased albumin." (PMID 33163000, 2020). "On his first laboratory tests, the baby had mild metabolic acidosis (PH: 7.24, PCO2:41 mmHg, PO2:60 mmHg, HCO3:17.6 mEq/L, BE:− 9.4 mEq/L), lymphopenia (2.4 × 109 /L), the elevated LDH (1645 U/L normal: ≤450 U/L), and normal CRP (6 mg/dl)." (PMID 32958069, 2020). "The laboratory abnormalities observed in this study were leucopenia, lymphopenia, elevated D-dimer, ESR, IL-6, serum ferritin, CRP, and LAC, which were related to sustained inflammatory response." (PMID 32792492, 2020). "Blood tests revealed decreased oxygen saturation (94%), increased C-reactive protein (CRP) level (5.38 mg/dL; reference <0.5 mg/dL), and lymphopenia (0.69 × 103 cells/mm3; reference range 0.8–4 × 103 cells/mm3)." (PMID 32396504, 2020). "Thrombocytopenia (54 × 109/L), lymphopenia (0.54 × 109/L), prolonged APTT (60 s), transaminitis (AST 81 IU/L; ALT 41 IU/L), elevated C-reactive protein (37 mg/L) and ferritin (431 μg/L) were observed upon hospital admission." (PMID 32665677, 2020). "In a case series of nine pediatric patients, three patients showed leukopenia and lymphopenia, two showed increased lactate dehydrogenase (LDH), and nine had high C- reactive protein (CRP) and erythrocyte sedimentation rate (ESR)." (PMID 32577325, 2020). "To simplify and contextualize this aggregate IH risk, we used a simple scoring system to categorize participants according to lymphopenia status, RDW, and CRP level." (PMID 31790569, 2019). "Biological abnormalities observed during CHIKV infection were lymphopenia (41.1%), leukopenia (51.6%), elevated transaminases (30.5%-46.3%) and high LDH (46.3%) and CRP (60.0%)." (PMID 29065182, 2017). "Absence of retro-orbital pain, neutropaenia and thrombocytopaenia, negative NS 1 and presence of rash at onset of febrile illness, lymphopenia, high ESR and C-reactive protein (CRP) are important clues in differentiation between the two." (PMID 28810894, 2017). "Many pretreatment blood-based measurements of systemic inflammatory response are prognostic in patients with RCC, including NLR, CRP, MLR, GPS, granulocyte-to-dendritic cell (DC) ratio, neutrophilia, thrombocytosis, lymphopenia and so on." (PMID 27661105, 2016). "Full blood count was normal but for moderate lymphopenia; there was moderate elevation of alanine transaminase (ALT) to 177 U/L, increasing to 430 U/L one week later, and C-reactive protein (CRP) was 40 mg/L." (PMID 30270856, 2016). "Laboratory tests revealed leukopenia, neutropenia, lymphopenia and monocytosis (WBC 3,3×10μ3/ μL, 1,6×10μ3/ μL, 1,3 ×10μ3/ μL and 10,9% respectively, ESR and C-reactive protein (CRP) were within limits ESR -12/lh, CRP -0.1 mg/l." (PMID 25201416, 2014). "Laboratory tests indicated lymphopenia (410/μL), and elevated levels of aspartate aminotransferase (AST; 136 IU/L), lactate dehydrogenase (LDH; 740 IU/L), and C-reactive protein (CRP; 0.9 mg/dL)." (PMID 24139226, 2013). "ROC analysis revealed a good negative predictive value but a poor positive predictive value of both lymphocytopenia and NLCR and performance was inferior to that of C-reactive protein." (PMID 23506136, 2013). "The NLCR was found to correlate with parasitaemia, but both lymphocytopenia and the NLCR were inferior to C-reactive protein as markers for severe disease in patients with imported malaria." (PMID 23506136, 2013). "In conclusion, the NLCR was found to correlate with parasitaemia, but both lymphocytopenia and the NLCR were inferior to CRP as markers of severe disease in patients with imported malaria in direct back-to-back comparisons." (PMID 23506136, 2013).
lymphopenia (continued). "Laboratory tests abnormalities included lymphopenia (59%), elevated serum LDH (84%), CK (37%), AST (56%), ALT (38%) and CRP (63%)." (PMID 20513239, 2010). "The results of laboratory tests indicated lymphopenia, hypoproteinemia, elevated LDH and CRP levels, which were consistent with other reports." (PMID 20513239, 2010). "RSV induced a consistent systemic inflammatory response in both waves, characterized by elevated IL-6 and CRP levels, neutrophilia, lymphopenia, and increased neutrophil-to-lymphocyte ratios, with no relevant inter-wave differences." (PMID 42279045, 2026). "Hematological changes, including lymphopenia, eosinopenia, and neutrophilia, alongside increased NLR, CRP, IL-6, ferritin, and D-dimer levels, have been consistently associated with disease prognosis and mortality in SARS-CoV-2 infection across various geographical regions." (PMID 41472264, 2025). "In contrast to conventional measures like CRP or total leukocyte count, SII concurrently reflects both pro-inflammatory activity (neutrophilia and thrombocytosis) and stress-induced immune suppression (lymphopenia)." (PMID 40804906, 2025). "In our patient, the presentation of 2 days of persistent fever, elevated inflammatory markers (CRP, ferritin, fibrinogen, LDH, and procalcitonin), respiratory involvement, altered consciousness, high liver enzymes, gastrointestinal symptoms, and lymphopenia was highly suggestive of MIS‐C." (PMID 40948697, 2025). "Initial laboratory investigations revealed leukopenia with lymphopenia and severe thrombocytopenia, and a mild inflammatory response with elevated fibrinogen and erythrocyte sedimentation rate (ESR), and a positive latex C-reactive protein (CRP)." (PMID 41003571, 2025). "Laboratory investigations showed lymphopenia, a CRP level of 36.9 mg/L, and negative sputum smear and respiratory virus screening." (PMID 39118282, 2024). "A study done in similar set up in Bangladesh during COVID-19 era, the study team found that the critically ill patients had lymphopenia, high D-Dimer and CRP level than those who are not critically ill." (PMID 38547199, 2024). "The second subphenotype (21% prevalence) had mid-aged individuals with none or few comorbidities, lymphopenia and elevated CRP." (PMID 38915125, 2024). "In relation to laboratory markers, lymphopenia (Z = 2.50; p = 0.012), thrombopenia (Z = 2.40; p = 0.016) and higher levels of serum LDH (Z = 2.89; p = 0.004), C-reactive protein (Z = 2.86; p = 0.004), procalcitonin (Z = 3.58; p < 0.001) and IL-6 (Z = 2.82; p = 0.005) were associated with mortality." (PMID 39023662, 2024). "At the time of pneumonia, RA was in remission (DAS28VSG 2.1) without leukopenia or neutropenia (total leucocytes 6900× mm3, and total neutrophils 6430× mm3) but severe lymphopenia (130× mm3) and mild thrombocytopenia (total platelets 129,000× mm3), ESR 2 mm/hour, CRP 46.1 mg/L." (PMID 39768600, 2024). "Laboratory investigations showed lymphopenia, a CRP level of 18.9 mg/L, and negative sputum smear and the respiratory virus screening." (PMID 39118282, 2024). "Lymphopenia, neutrophilia, and thrombocytopenia were more pronounced in non-surviving patients, while the levels of CRP, AST, creatinine, ferritin, AST, troponin I, urea, magnesium, and potassium were higher in the non-surviving group than the survival group." (PMID 39281667, 2024). "The patient's clinical condition coincided with the derangement of biomarkers described in the literature, including lymphopenia, increased neutrophil/lymphocyte ratio (NLR), decreased lymphocyte/C-reactive protein ratio (LCR), as well as elevated inflammatory markers such as CRP and D-dimers." (PMID 37189864, 2023). "White blood cells (WBC), C‐reactive protein (CRP), erythrocyte sedimentation rate (ESR), neutrophilia, and lymphopenia peaked 3 days post‐ICH, and they showed much stronger correlations with clinical and neuroimaging variables, when compared to the admission values." (PMID 35762501, 2023).
lymphopenia (continued). "Initial blood testing revealed a normal whole blood count (WBC), mild lymphopenia, and high CRP concentration; an HIV test was negative." (PMID 36821021, 2023). "Lymphopenia increased the probability of mortality by more than two times (OR: 2.568; 95% CI (0.962–6.852)), but this was not the case for D-dimer and C-reactive protein." (PMID 38130842, 2023). "The clinical characteristics of SARS CoV-2 can mimic the flare-up of rheumatic diseases, such as high-grade fever, arthralgia, myalgia, and fatigability, in addition to lymphopenia, a high erythrocyte sedimentation rate (ESR), C-reactive protein (CRP), and creatine kinase (CK)." (PMID 37675163, 2023). "The factors associated with a worse outcome of tocilizumab use in terms of hospital stay were: baseline situation at the start of tocilizumab treatment requiring IMV or supplemental oxygen, elevated levels of ferritin, GOT, GPT, CRP, LDH, lymphopenia, and low PAFI values." (PMID 36012968, 2022). "However, we did observe signs of inflammation through increased levels of hepatic transaminases and C-reactive protein (CRP) throughout their follow-up, and a transient lymphopenia at DPI 2 (respectively)." (PMID 35603150, 2022). "Clinical biochemistry and hematology results revealed C-reactive protein increases, neutropenia, and lymphopenia, but these changes were not considered adverse due to their short-lived and asymptomatic nature." (PMID 36582243, 2022). "The factors associated with worse outcome of tocilizumab use in terms of hospital stay were: baseline status at the start of tocilizumab treatment requiring IMV or supplemental oxygen, elevated levels of ferritin, GOT, GPT, CRP, LDH, lymphopenia, and low PaFi values." (PMID 36012968, 2022). "In a study conducted in the west of Iran, lymphopenia, LDH, CRP, and WBC with clinical indicators including tachypnea and hypoxia were taken into consideration as predictors for the length of hospital stay, and the need for important treatment measures as well as the severity of COVID-19 infection." (PMID 35685588, 2022). "Blood test revealed normal blood count (no lymphopenia or lymphocytosis or eosinophilia), slight increase of procalcitonin serum level (0.14 ng/mL), C‐reactive protein (CRP, 12.1 mg/dL), and liver enzymes (GOT, GPT, LDH, GGT fourfold levels)." (PMID 32986289, 2021). "This ratio has a better sensitivity during the acute phase of inflammation, as CRP levels increase earlier than neutrophilia or lymphopenia in acute inflammation regardless of its origin (infection, cancer, autoimmune disease)." (PMID 34945746, 2021). "Also, the majority of patients who died had raised leucocyte count (76.7%), lymphopenia (97.1%), hypoalbuminemia (95.4%), raised LDH (93.6%), raised CRP (98.8%), D-dimer (98.3%), serum ferritin (92.4%) and interleukin 6 level (95.4%)." (PMID 34548976, 2021). "Regarding their lab tests, they had the lowest hemoglobin results (12 vs. 14 g/dL; p = 0.005), the highest lymphopenia results (750 vs. 1,020/mm3; p = 0.003), and the highest D-dimer (3285.5 vs. 1,285 ng/mL FEU; p = 0.004) and CRP (31.9 vs. 17.4 mg/dL; p < 0.001) values." (PMID 34150790, 2021). "In our cohort, we identified an increase in creatinine, urea, CRP, and D-dimer levels as well as lymphopenia only in the FATAL group in relation to the GW group, but not in relation to ICU patients." (PMID 34685377, 2021). "Patients with viremia were older (p = 0.006), had poorer baseline oxygenation (PaO2/FiO2; p < 0.001), more severe lymphopenia (p < 0.001) and higher LDH (p < 0.001), IL-6 (p = 0.021), C-reactive protein (CRP; p = 0.022) and procalcitonin (p = 0.002) serum levels." (PMID 34162948, 2021). "At onset, laboratory features showed leukopenia (2.38 × 103/uL), lymphopenia (0.89 × 103/uL), hypergammaglobulinemia (22.31 g/l) and normal C-reactive protein (CRP) (< 0.5 mg/dl); antinuclear antibody (ANA) and anti-dsDNA were negative." (PMID 34530845, 2021).
lymphopenia (continued). "By the time of this study, testing was limited to 7.46 per 10,000 inhabitants, thus, clinical suspicion of patients with respiratory symptoms with elevation of CRP, LDH, and lymphopenia, can be useful markers for triage in settings unable to rely on molecular or radiological tests." (PMID 33999930, 2021). "Initial laboratory criteria for strongly suspected MIS-C as elevated C-reactive protein (CRP) ≥30 mg/L and/or erythrocyte sedimentation rate (ESR) >40 mm/h plus lymphopenia <1000 or thrombocytopenia <150 × 103 or hyponatraemia <135 mmol/L were met in all 13 MIS-C patients." (PMID 34208057, 2021). "Lymphopenia, neutrophilia, LDH, D-dimer and CRP may be related to the progression of COVID-19 disease according to previous studies." (PMID 33789703, 2021). "Blood sampling at admission showed lymphopenia, thrombopenia and neutrophil polynucleosis, without elevation of C reactive protein." (PMID 33803267, 2021). "Several biomarkers predict a poor outcome of the disease, including increased levels of IL-6 (interleukin 6), serum ferritin, CRP (C-reactive protein), LDH (lactate dehydrogenase), D-dimer, and fibrinogen, as well as reduced levels of antithrombin and lymphopenia." (PMID 34395368, 2021). "Common laboratory markers such as CRP and lymphopenia do not appear to be usable in the evaluation of severity of illness among children with COVID-19 disease; nevertheless, further investigations are needed to confirm the findings of this study." (PMID 35096716, 2021). "Age, high CCI, elevated C-reactive protein (CRP), ferritin, D-dimer, lactate dehydrogenase (LDH), urea, creatinine, lymphopenia, neutrophilia and thrombocytopenia within ±24-h of admission were independently associated with death within the first week in the multivariate analysis." (PMID 33421989, 2021). "Similarly to adults, laboratory tests showed an increase in C-reactive protein (CRP) (moderate), transaminases, lactate dehydrogenase, D‐dimer and creatine kinase, as well as leukopenia (primarily lymphopenia)." (PMID 32533443, 2020). "Patients with new lesions were more likely to have lymphopenia (P=0.041) or increased C-reactive protein (CRP) levels (P<0.001) than those without new lesions." (PMID 32922203, 2020). "More patients with new lesions showed lymphopenia and increased CRP than those without (P=0.041 and P<0.001, respectively)." (PMID 32922203, 2020). "Chest CT showed ground glass opacities with a peripheral distribution, with greater compromise of bases and areas of crazy paving, and initial lab tests showed lymphopenia (1010 × 10 3/μl), and lightly elevated LDH (343 U/l), D-dimer (0.88 μg/ml) and CRP (5.09 mg/dl)." (PMID 32664810, 2020). "Disease severity in hospitalized patients is characterized by severe pneumonia associated with overt inflammatory reaction characterized by high C-reactive protein (CRP) and interleukin-6 (IL-6), low albumin, high sedimentation rate, low eosinophils, and lymphopenia." (PMID 32849908, 2020). "C-reactive protein, lymphopenia, and leukopenia were also presented, but no hypoalbuminemia, LDH, hepatic enzymes, bilirubin, nor creatinine were altered." (PMID 32331519, 2020). "Most common laboratory findings were increased C-reactive protein (CRP) levels (707/1388; 51%), increased lactate dehydrogenase (LDH) levels (700/1678; 41.7%), lymphocytopenia (634/1737; 36.5%), increased D-dimer levels (457/1590; 28.7%), and leukocytopenia (464/1668; 27.8%)." (PMID 33110589, 2020). "Moreover he had lymphopenia (1.9× 109 /L), the elevated LDH (963 U/L normal: ≤450 U/L), and low CRP (1.9 mg/dl)." (PMID 32958069, 2020). "Recent research also demonstrated that severe patients had more prominent laboratory abnormalities (i.e., lymphopenia, elevated CRP levels) than non-severe patients." (PMID 32746805, 2020). "Considering elevated ESR and CRP levels were non-specific to IM, only interstitial pneumonia, lymphopenia, and median-to-high dose of GC were included into the logistic regression analysis." (PMID 30867045, 2019).
lymphopenia (continued). "We sought to test the hypothesis that lymphopenia may identify a population at enhanced risk, and those with multiple immunohematologic (IH) abnormalities (defined herein as lymphopenia and/or abnormal RDW or CRP levels) may have further reduced longevity." (PMID 31790569, 2019). "A significant effect was also found for the interaction (p = 0.043) between corticosteroids and lymphopenia in CRP values at day 3, with lower values in patients without lymphopenia receiving corticosteroids after adjustments for potential confounders." (PMID 31540339, 2019). "Our study found that patients who received corticosteroids presented differences in the systemic anti-inflammatory effect as measured by CRP at day 3, with variations related to the presence or absence of lymphopenia." (PMID 31540339, 2019). "In all cases of non-CONS-positive blood cultures, neither neutropenia, lymphopenia, monopenia nor eosinopenia were more commonly observed in patients with negative compared to positive CRP results." (PMID 24244325, 2013). "In contrast to studies in bacterial sepsis, where lymphocytopenia and NLCR were found to outperform CRP in predicting the presence of bacteraemia, lymphocyte counts and NLCR did not allow for an accurate discrimination between malaria patients with severe disease and those without." (PMID 23506136, 2013). "Most patients had elevated C-reactive protein (CRP) levels and lymphopenia." (PMID 15200814, 2004). "Our findings are consistent with these observations, reinforcing the prognostic roles of hypoalbuminemia and lymphopenia—two OPS components—while also highlighting the added value of incorporating CRP, a marker of systemic inflammation not captured by GNRI, PNI, or CONUT." (PMID 41470144, 2025). "His laboratory results included an elevated C-reactive protein (CRP) of 30 mg/L, erythrocyte sedimentation rate (ESR) of 43 mm/hr, and hemoglobin of 107 g/L, with a normal white blood cell (WBC) count (4.1 × 109 cells/L) and mild lymphopenia (0.9 × 109 cells/L)." (PMID 41233774, 2025). "Furthermore, laboratory findings indicated that more than half of the patients had increased C-reactive protein (92.3%), increased neutrophil count (92.3%), elevated ALT or AST (84.6%), electrolyte disorders (76.9%), lymphopenia (69.2%), eosinophilia (69.2%), and thrombocytopenia (61.5%)." (PMID 38442086, 2024). "Additionally, the extension of lung damage seen on a computerized tomography (CT) scan is also related to higher levels of inflammatory markers such as C-reactive protein (CRP) and other severity indicators such as lymphopenia, neutrophilia, lower oxygen saturation and partial oxygen pressure." (PMID 38687065, 2024). "Notably, there was neutrophilia accompanied by lymphopenia, while C-reactive protein (CRP) levels remained normal and no renal or hepatic function disturbances were observed." (PMID 39210364, 2024). "Laboratory tests revealed lymphopenia (lymphocyte count 660/μL), thrombocytopenia (platelet count 129,000/μL), non-hemolytic hypochromic anemia (10,9 g/dL), elevated C reactive protein (CRP) and erythrocyte sedimentation rate (ESR) (9,99 mg/dL and 28 mm/h, respectively)." (PMID 38238724, 2024). "Blood analyses revealed lymphopenia, normal or mildly elevated CRP, no pleocytosis." (PMID 37880789, 2023). "Additionally, our data show that IL-6 and CRP were higher in men than women, along with more severe lymphopenia in men, but independent of APLA positivity." (PMID 37626797, 2023). "The MIS-C patients who were older (P<0.001) had higher median peak values of CRP (P<0.001), IL-6 (P<0.001), ferritin (P<0.001), procalcitonin (P=0.002), left ventricular systolic dysfunction (P<0.001) and lymphopenia (P=0.01) when compared to those without AKI." (PMID 37954764, 2023). "However, our multivariate analysis showed that sIL-2R had the highest diagnostic accuracy for predicting intubation or death, compared with the other known negative predictive factors (ferritin, CRP, and lymphopenia)." (PMID 35458517, 2022).